CTNNB1 (catenin beta 1)
Diseases named in the same sentence as CTNNB1 in open-access papers (continued):
Sharing a sentence is not in itself a finding about the gene and the disease.
colorectal cancer (continued). "Moreover, the most popular genes were APC (in Wnt pathway), KRAS (in MAPK pathway) and PIK3CA (in PI3K pathway) in the colorectal cancer, pancreatic cancer, and gastric cancer while they were beta-catenin and CTNNB1 in liver cancer." (PMID 33127962, 2020). "Until now, there was no comprehensive association study of CTNNB1 gene with colorectal cancer patients in Pakistani Population." (PMID 31699039, 2019). "The vast majority of colorectal cancers (~90%) carry mutations in one of two genes involved in the canonical Wnt/β-catenin signalling pathway: the adenomatous polyposis coli (APC) and -catenin (CTNNB1) genes." (PMID 27902469, 2017). "It would be interesting to see whether SRI37892 can indeed effectively inhibit Wnt/β-catenin signaling in colorectal cancer cells harboring APC and CTNNB1 mutations." (PMID 29207657, 2017). "A vast majority of colorectal cancer (CRC) tumors contain mutations in genes encoding members of the Wnt signaling pathway, and nearly all of these mutations lead to stabilization and excessive accumulation of CTNNB1 protein." (PMID 27333864, 2016). "Only colorectal cancer predominantly harbours mutations in APC, whereas other cancer types (hepatocellular carcinoma, solid pseudopapillary tumours of the pancreas) have activating mutations in β-catenin (CTNNB1)." (PMID 26240067, 2015). "Therefore, we applied a comprehensive approach to systematically evaluate the tag single-nucleotide polymorphisms (tSNPs) in two key genes in the Wnt pathway, APC and CTNNB1, as predictors of colorectal cancer prognosis." (PMID 23405266, 2013). "In summary, this might be the first study to systematically evaluate the use of tSNPs in APC and CTNNB1 genes to predict outcomes in colorectal cancer patients." (PMID 23405266, 2013). "Finally, it is worth pointing out that CELF4, TCF7L2, FTO, RUNX1, RUNX3, and CTNNB1 have all been reported to be involved in the etiology of colorectal cancer." (PMID 23626757, 2013). "The CTNNB1 mutation frequency vary considerably also in colorectal cancer (1–60%) and melanomas (0.02–27%), apparently not related to geographical origin." (PMID 18541010, 2008). "In colorectal cancer, increased protein stability of the WNT effector β-Catenin is critical for tumorigenesis and mediated either by loss of function mutations and truncations within the APC gene or via mutations of the degron motive within CTNNB1, the gene encoding β-Catenin." (PMID 39443725, 2024). "Similarly, PKA activation in APC-mutant colorectal cancer could exert important effects on CTNNB1 via inhibition of GSK3." (PMID 36692000, 2023). "For example, CTNNB1 is the gene encoding for β-catenin and the deregulation of the WNT/CTNNB1 (β-catenin) pathway is a well-established event in the carcinogenic process in several neoplasias, including colorectal cancer, hepatocellular carcinoma and cutaneous melanoma, among others." (PMID 35008260, 2021). "Finally, we provide evidence that in colorectal cancer patient tissue, CTNNB1 mutations that eliminate Ser45 or Thr41 do not result in elevated β-catenin activity as assessed by Wnt target gene expression." (PMID 32751567, 2020). "The presence of APC mutations as an alternative to CTNNB1 mutations in some POLE‐mutant endometrial cancers is an exemplar, and there are likely to be others, such as NF1 and RB1 mutations in endometrial cancer and atypical (Q61P, K117 N, and A146T) KRAS mutations in colorectal cancer." (PMID 29604063, 2018). "Mutations in FBXW7 and CTNNB1 were associated with high-grade disease, the latter suggesting that activation of the Wnt pathway through CTNNB1 rather than APC mutation might predispose to poorly differentiated colorectal cancers." (PMID 30042065, 2018).
colorectal cancer (continued). "Our studies revealed that the quinazoline compounds repress Wnt/β-catenin signaling without altering the level of β-catenin protein in colorectal cancer cells harboring mutations in CTNNB1 or APC, suggesting that they act on the downstream elements of the pathway." (PMID 26820295, 2016). "Genetic mutations in adenomatous polyposis coli (APC) and catenin (cadherin-associated protein) beta 1 (CTNNB1), the components of the Wnt/β-catenin signaling pathway, are the major contributors of colorectal cancer although they are typically not the key factors associated with breast cancer." (PMID 25499975, 2014). "While genetic mutations of certain components of the Wnt/β-catenin pathway, such as APC and CTNNB1, are significant contributing factors for colorectal cancers, they are typically not the predominate mechanism associated with many other types of cancer such as breast and prostate cancers." (PMID 22195040, 2011). "Two colorectal cancer patients harboured a mutation in the CTNNB1 gene, that did not occur at the Ser/Thr phosphorylation sites, but would result in an amino acid alteration at codons 22 and 29, the effects of which are unknown." (PMID 16356174, 2005). "For example, inhibition of protein phosphatase 2 activator (PTPA) in colorectal cancer leads to activation of oncogenic pathways (e.g., MAPK, catenin beta 1 [CTNNB1]) and cellular stress responses." (PMID 40659633, 2025). "In colorectal cancer (CRC), LSM12 is highly expressed and participates in the proliferation, invasion, and apoptosis of CRC cells through the WNT/CTNNB1 pathway." (PMID 40425760, 2025). "In the current study, we employed two human colorectal cancer cell lines, HT29 and SW480; these cells carry wild-type CDH1 (E-cadherin) and CTNNB1 (β-catenin), but mutant APC, and exhibit active Wnt/β-catenin signaling." (PMID 36072467, 2022). "The expression of CTNNB1, its target genes, and TERT have been reported at the invasive edges of colorectal cancer." (PMID 34439356, 2021). "In other study, the supplementation of pomegranate extract in patients with colorectal cancer had a significant down-regulating effect on the expression of colorectal cancer-related genes such as CD44, CTNNB1, CDKN1A, and EGFR in surgical colon samples." (PMID 33322700, 2020). "Three-fourths of colorectal cancers possessed APC alterations and about one in four of these cases possessed also concomitant alterations in other genes of the WNT/β-catenin/APC pathway, including RNF43, CTNNB1, and TCF7L2." (PMID 40061138, 2025). "Besides, we have revealed that LINC02418 plays a significant part in the activation of Wnt pathway and promoting colorectal cancer progression via binding to YBX1 and IGF2BP1 protein to perform transcriptional and post-transcriptional regulation of CTNNB1." (PMID 40082414, 2025). "Additionally, the POP112 line did not harbour mutations or deep amplifications or deletions in the WNT pathway members defined as colorectal cancer drivers APC, AXIN1, AXIN2, CTNNB1, GSK3B or RNF43, and only a shallow deletion in ZNRF3." (PMID 38324534, 2024). "Liu and colleagues reported that CTNNB1 (β-catenin), a core constituent of the WNT signaling pathway, could promote the development and progression of colorectal cancer and enhance the stemness of cancer stem cells." (PMID 36439454, 2022).
colorectal cancer (continued). "In colorectal cancer, LINC00665 can interact with U2AF2, enhance the binding between U2AF2 and CTNNB1 mRNA, and increase the stability of CTNNB1 mRNA, thereby further activating the Wnt/β-catenin signaling pathway and stimulating the proliferation and invasion of colorectal cancer cells." (PMID 35563845, 2022). "Similarly, PART1 was shown to promote malignant progression of colorectal cancer through the miR-150-5p/LRG1 axis and by sponging miR-150-5p to up-regulate the expression of CTNNB1 and activate Wnt/β-catenin signaling." (PMID 34072264, 2021). "For the most part however, and unlike the situation encountered in colorectal cancer, genetic mutations in APC, AXIN or CTNNB1 are virtually non-existent in human breast tumors." (PMID 32083079, 2020). "However, the number of colospheres significantly decreased in primary colorectal cancer P1, HT-29, and SW620 cells after CTNNB1 was knocked down by RNA interference." (PMID 28137278, 2017). "There is no dispute that Wnt pathway activation and CTNNB1 protein accumulation can be potent drivers of a number of cancer types, particularly colorectal cancer." (PMID 27333864, 2016). "Of note, unlike colorectal cancer, breast cancer cells exhibit infrequent genetic mutations of APC or β-catenin/CTNNB1 (refs 49, 50), which implies that additional regulatory mechanisms of Wnt signalling exist." (PMID 26843124, 2016). "Furthermore, the mutation frequency of CTNNB1 was low in adenomas (12.2%), a finding that is in accordance with most of the previous analyses on colorectal adenomas and with the observation that CTNNB1 mutations mainly occur in hereditary nonpolyposis colorectal cancer and in tumors exhibiting MSI." (PMID 24212608, 2010). "As AMBRA1 affected CTNNB1 transcription via ALDH1B1, which is a crucial CSC marker of colorectal cancer, we next investigated whether AMBRA1 expression affects the mRNA levels of several CSC-related β-catenin target genes, including LGR5, HIF1a, ALDH1A3, CD24, and SOX4." (PMID 34769507, 2021). "These different results we obtained support the view that the changes in CTNNB1 mRNA level may not be useful in colorectal cancer diagnosis." (PMID 33237662, 2021). "Dose-dependent reduction in cancer specific mortality in breast cancer patients with > 21 MET-h/wk (multivariate adjusted RR = 0.51, p < 0.05), in men&women with CTNNB1-negative colorectal cancer patients with > 18 MET-h/wk (multivariate adjusted RR = 0.33,p < 0.05)." (PMID 28978180, 2017). "However, in HCT116 colorectal cancer cells, knockdown of CTNNB1 did not increase TCF7L1 protein levels, and CTNNB1 stabilization by addition of Wnt3a showed only a modest decrease in TCF7L1 protein." (PMID 27333864, 2016). "It was discovered that colorectal cancers possessed significant differences in their genomic profile dependent on whether the WNT/β-catenin/APC pathway was activated through alterations in APC or through alterations in three alternative genes of the pathway, RNF43, CTNNB1, and TCF7L2." (PMID 40061138, 2025). "Thus, we chose two human colorectal carcinoma (CRC) cell lines DLD-1 and HCT116, which exhibit elevated level of active CTNNB1 to generate disease relevant CB-based screening cell lines." (PMID 31544816, 2019). "Colorectal cancers with alterations in RNF43, CTNNB1, and TCF7L2 without APC alterations presented more commonly MSI and a high TMB." (PMID 40061138, 2025).
hepatocellular carcinoma (159 papers, 2011 to 2026). A malignant tumor that arises from hepatocytes. "For instance, CTNNB1 mutations are only present in a subset of hepatocellular carcinoma, limiting the generalizability of corresponding targeted therapies." (PMID 41050070, 2025). "Hepatocellular carcinoma (HCC) patients with CTNNB1 mutations frequently exhibit anti-PD1 therapeutic resistance." (PMID 39192657, 2025). "Within the same catalog, out of 5793 hepatocellular carcinoma samples, 20% displayed CTNNB1 mutations, out of which 83.78% experienced missense substitution mutations, as seen in medulloblastoma patients." (PMID 40564017, 2025). "Mutations in the CTNNB1 oncogene are present in medulloblastoma, hepatocellular carcinoma, colon and ovarian cancers." (PMID 40564017, 2025). "The genetic polymorphisms in Ctnnb1 gene were reported to affect tumor development, therapeutic responses, and survival in patients with hepatocellular carcinoma (HCC)." (PMID 41415834, 2025). "High morphological heterogeneity was particularly observed in CTNNB1‐mutated adenomas, as recently reported in hepatocellular carcinomas harbouring mutations in the β‐catenin gene." (PMID 39167619, 2024). "In studies focusing on hepatocellular carcinoma with Catenin beta 1 (CTNNB1) mutations, circFOXP1 expression was found to be dysregulated in liver cancer tissues." (PMID 39606233, 2024). "First, we show that both CBEs and ABEs allow modeling hotspot mutations in the most commonly mutated gene in hepatocellular carcinoma, CTNNB1, and that evolved variants of SpCas9 can be used to increase the targeting space of base editors in organoids." (PMID 37591832, 2023). "Lines of evidence have demonstrated that mutations in CTNNB1 can activate the Wnt signaling pathway and appear to be major events in hepatocellular carcinoma." (PMID 35061901, 2022). "While patients with hepatocellular carcinoma, especially those with CTNNB1 mutations, have an overall defective urea cycle and increased expression of GS, there exists a subset of patients with low GS expression that is associated with mTORC1 hyperactivation." (PMID 36256480, 2022). "In hepatocellular carcinoma, gain-of-function mutations of CTNNB1 (20–25%) and loss-of-function mutations of AXIN1 and AXIN2 are frequently observed." (PMID 35327645, 2022). "A circRNA derived from CTNNB1 locus promotes hepatocellular carcinoma cell progression via encoding a new 370-aa β-catenin protein which stimulating the Wnt signaling pathway." (PMID 34093821, 2021). "Together with CTNNB1 mutations, hTERT mutations have been shown to be associated with hepatocellular carcinomas and adenomas." (PMID 34235021, 2021). "circ-CTNNB1 stimulates the Wnt signaling pathway to drive hepatocellular carcinoma progression by encoding a new 370-aa protein." (PMID 34168984, 2021). "We therefore looked for associations between SNV burden with CTNNB1 mutation in hepatocellular cancer, and with TERT promoter mutation in thyroid cancer." (PMID 32859912, 2020). "DANCR was reported to associate to the CTNNB1 gene in hepatocellular carcinoma, thereby protecting it from inhibitory miRNAs; however, we were unable to detect an association under our conditions (data not shown)." (PMID 33302540, 2020). "Frequent heterozygous mutations in hotspot region of exon 3 in CTNNB1 have been described for different tumour entities such as hepatocellular carcinoma, solid pseudopapillary tumour and desmoid fibromatosis." (PMID 33115416, 2020). "A circRNA derived from CTNNB1 exons facilities cell proliferation and metastasis by encoding a novel 370‐amino acid CTNNB1 isoform and activating the Wnt signalling pathway in hepatocellular carcinoma." (PMID 32783378, 2020).
hepatocellular carcinoma (continued). "Previous studies declare CTNNB1 mutation is related to several cancers such as hepatocellular carcinoma, medulloblastoma, ovarian cancer, and pilomatricoma." (PMID 30929091, 2019). "Up to 41% of hepatocellular carcinomas (HCCs) result from activating mutations in the CTNNB1 gene encoding β-catenin." (PMID 31575545, 2019). "Somatic activating mutations in CTNNB1 have been detected in a number of tumors, but the highest frequency is observed in hepatocellular carcinoma (HCC)." (PMID 29383099, 2017). "Then, we examined the effect of H2 in two cell lines, HCT-116 colon cancer cells and HepG2 liver carcinoma cells, which carry mutations in CTNNB1 encoding β-catenin at its phosphorylation sites." (PMID 27558955, 2016). "The rs3864004 was located in the promoter region of the CTNNB1 and its polymorphism has been reported to be associated with development and survival of hepatocellular carcinoma." (PMID 27769064, 2016). "In conclusion, we identified TERT promoter and CTNNB1 mutations as the most frequent somatic genetic alterations observed in hepatocellular carcinoma, indicating its pivotal role in hepatocarcinogenesis." (PMID 27661004, 2016). "The hepatoblastoma cell line, Huh-6, carried a missense mutation of G34G > V, a known variant of CTNNB1 while the hepatocellular carcinoma cell line, Huh-7, was wild type CTNNB1." (PMID 21992464, 2011). "However, the CTNNB1 oncogene—encoding β-catenin—is also frequently mutated in hepatocellular carcinoma, resulting in aberrant WNT signalling that promotes cell growth." (PMID 41261129, 2026). "CTNNB1 mutations are thought to characterize the immune‐excluded class of hepatocellular carcinoma and may be a biomarker for predicting resistance to immune checkpoint inhibitors." (PMID 35040184, 2022). "However, our analysis did not identify a number of known mutational cancer drivers, for example, CTNNB1 in hepatocellular carcinoma, PIK3CA in breast cancer and NFE2L2 in lung squamous cell carcinoma." (PMID 34313788, 2021). "Furthermore mutations in CTNNB1, which encodes Beta-catenin are associated with increased Wnt signaling were identified in ∼ 20% of patients with hepatocellular carcinoma (HCC), including a patient with primary PFIC-2 diagnosis." (PMID 26116792, 2015). "Gain-of-function mutations in CTNNB1 (encoding for b-catenin) leading to deregulated Wnt/β-catenin signaling are frequently observed in patients with hepatocellular carcinoma (HCC)." (PMID 40442146, 2025). "Published data on the analysis of CTNNB1 exon 3 mutations in HCC were retrieved from PubMed using the keywords “CTNNB1”, “exon 3”, “mutations”, and “hepatocellular carcinoma”." (PMID 40243493, 2025). "Downregulation of SDC4 and RAB27A in human hepatocellular carcinoma (HCC) samples with CTNNB1 mutations." (PMID 39008536, 2024). "According to cBioPortal database, APC is the top 1 mutated tumor suppressor gene in colon adenocarcinoma (COAD, 68.6% mutation rate) and CTNNB1 (30.6% mutation rate) is the most frequently mutated proto-oncogene in hepatocellular carcinoma (HCC)." (PMID 36703130, 2023).